S100A4 (S100 calcium binding protein A4)
Diseases named in the same sentence as S100A4 in open-access papers (continued):
Sharing a sentence is not in itself a finding about the gene and the disease.
leukemia (8 papers, 2015 to 2025). A malignant (clonal) hematologic disorder, involving hematopoietic stem cells and characterized by the presence of primitive or atypical myeloid or lymphoid cells in the bone marrow and the blood. "To examine the effect of S100A4 deficiency on the proliferation and chemoresistance of leukemia cells, we employed S100A4 RNA interference in leukemia cells treated with PBS or BM-MSC-exos." (PMID 33789743, 2021). "To examine the effect of S100A4 deficiency on migration and invasion, we employed S100A4 RNA interference in leukemia cells." (PMID 33789743, 2021). "Emerging evidence suggests that S100A4 is overexpressed in leukemia and is associated with a poor prognosis, This is consistent with the results of our study." (PMID 33789743, 2021). "S100A4 has been previously associated with poor prognosis in several solid tumors and in leukemia." (PMID 31611628, 2020). "By performing network analysis based on physical interactions and co-expression, we demonstrated that the upregulated genes LGALS1, S100A10, EMP3, and S100A4 in the residual leukemia-like cells were involved in a functional module with LGALS1 as a hub gene." (PMID 36543880, 2023). "Mechanistically, BM-MSC-exos promoted the proliferation, invasion and chemoresistance of leukemia cells via upregulation of S100A4." (PMID 33789743, 2021). "Previous studies have shown that increased expression of S100A4 affects proliferation and drug resistance in leukemia." (PMID 33789743, 2021). "Further studies are warranted to determine the mechanism by which knockdown of S100A4 reduced proliferation, invasion, and chemoresistance of leukemia cells, and rescued the phenotypes induced by treatment with BM-MSC-exos." (PMID 33789743, 2021). "Downregulating S100A4 clearly suppressed the proliferation, invasion, and chemoresistance of leukemia cells after treatment with BM-MSC-exos." (PMID 33789743, 2021). "The effect of S100A4 on the migration and invasion of leukemia cells was observed with transwell migration and invasion assays." (PMID 33789743, 2021). "Our results suggest that BM-MSC-exos influence the proliferation, invasion and chemoresistance of leukemia cells via the upregulation of S100A4." (PMID 33789743, 2021). "We also observed S100A4 expression in all leukemia cell lines analyzed with six of the ten lines having prominent nuclear expression of the protein." (PMID 31611628, 2020). "The functional implication of altered S100A4 expression, subcellular localization, and mechanisms of action in cancers (especially leukemia) remain unidentified." (PMID 31611628, 2020). "We next examined the consequences of knocking down S100A4 expression in leukemia cell lines." (PMID 31611628, 2020). "However, when S100A4 targets leukemia cells, it also promotes cell proliferation." (PMID 38872805, 2024). "Similarly, after S100A4 knockdown, fewer leukemia cells invaded the membrane." (PMID 33789743, 2021). "Our data suggested that S100-A4 may be a novel target for improving leukemia therapy." (PMID 25628518, 2015). "We first verified the upregulation of S100A4 mRNA in leukemia cells treated with BM-MSC-exos by qPCR and S100A4 protein abundance by western blotting." (PMID 33789743, 2021). "We also found that BM-MSC-exo-treated leukemia cells formed significantly more colonies than leukemia cells treated with BM-MSC-exos and S100A4-siRNA (P < 0.05)." (PMID 33789743, 2021). "S100A4 is vital in the BM-MSC-exo-driven proliferation, invasion and chemoresistance of leukemia cells and may serve as a potential target for leukemia therapy." (PMID 33789743, 2021). "Moreover, while more leukemia cells migrated after treatment with BM-MSC-exos than in the NC group (P < 0.05), the migration ability of leukemia cells with S100A4 knockdown and BM-MSC-exos treatment was weaker than that of leukemia cells with BM-MSC-exos treatment alone (P < 0.05)." (PMID 33789743, 2021).
lung adenocarcinoma (7 papers, 2012 to 2022). A carcinoma that arises from the lung and is characterized by the presence of malignant glandular epithelial cells. "S100A4 promotes lung tumor development; a high expression of S100A4 in lung adenocarcinoma tissue is associated with poor prognosis." (PMID 35214097, 2022). "Clinical investigation demonstrated that high expression level of S100A4 was associated with tumor size and advanced tumor grades of lung adenocarcinoma patients." (PMID 29449540, 2018). "We found that in lung adenocarcinoma patients, S100A4 elevation was associated with reduced overall survival as well as lymphovascular invasion, a marker of poor prognosis in many cancers." (PMID 27127879, 2016). "Our results demonstrated that S100A4 expression in tumor tissues from lung adenocarcinoma patients is closely linked to tumor progression patient-derived tissues and this study is the first report in which S100A4 is shown to promote lung tumor growth by downregulating autophagy." (PMID 29449540, 2018). "Furthermore, we found that S100A4 overexpression was associated with the presence of lymphovascular invasion and decreased overall survival among patients with lung adenocarcinoma (median survival: 29.5 versus 70 months, hazard ratio 2.62, 95% confidence interval 1.133 to 6.035, P = 0.0243)." (PMID 27127879, 2016). "We found that only a few S100A4+ cells were detected in paracarcinoma tissues, however, various ranges of immunostaining intensities were observed in lung adenocarcinoma tissues." (PMID 29449540, 2018). "In this study, we found that upregulation of S100A4 expression in lung adenocarcinoma tissues is closely related to advanced tumor grades." (PMID 29449540, 2018). "We found that S100A4 was preferentially overexpressed in lung adenocarcinoma when compared to squamous cell carcinoma, which was confirmed using a publicly available gene expression dataset." (PMID 27127879, 2016). "Our results suggest that S100A4 expression may influence tumor size and advanced tumor grades in lung adenocarcinoma cases." (PMID 29449540, 2018). "In this study, we found that S100A4 was significantly upregulated in lung adenocarcinoma tissues." (PMID 29449540, 2018). "As published in other reports, we found that S100A4 expression was elevated in lung adenocarcinoma." (PMID 27127879, 2016). "In patient-derived tissues, S100A4 is preferentially elevated in lung adenocarcinoma." (PMID 27127879, 2016). "Furthermore, we have demonstrated that S100A4 induces expression of ephrin-A1 in lung adenocarcinoma cell lines, and that the expression of these potential biomarkers is significantly associated in the primary tumor samples." (PMID 22853000, 2012). "It has been reported that elevated S100A4 expression was highly correlated with poor prognosis in lung adenocarcinoma, lung squamous cell carcinoma and other subtypes of non-small celllung carcinomas." (PMID 29449540, 2018). "About 14.17% of the lung adenocarcinoma tissues were assessed to be negative expression, and 66.67% and 19.17% of the lung adenocarcinoma tissues were detected with low and high expression of S100A4, respectively." (PMID 29449540, 2018).
medulloblastoma (7 papers, 2007 to 2021). A malignant, invasive embryonal neoplasm arising from the cerebellum. "S100A4 promotes angiogenesis and extracellular matrix degradation through its upregulation of specific matrix metalloproteases and high levels of S100A4 expression are associated with metastatic progression in a wide range of cancers including medulloblastoma." (PMID 17579622, 2007). "Current findings are therefore consistent with a role for the oncogenic activation of S100A4 by hypomethylation-associated expression upregulation in medulloblastoma tumourigenesis." (PMID 17579622, 2007). "S100A4 protein serves as a direct signaling target of receptor tyrosine kinase 2 (ERBB2) in medulloblastoma through a pathway involving phosphatidylinositol 3 kinase AKT (PI3K/AKT), which is ultimately blocked by the ERBB tyrosine kinase inhibitor OSI774." (PMID 34148033, 2021). "The most common malignant brain tumor in children, medulloblastoma, displays up-regulated levels of S100A4." (PMID 33918416, 2021). "The levels of ERBB2 and S100A4 tightly correlated also in samples of primary medulloblastoma." (PMID 33918416, 2021). "Overexpression of several of the S100 proteins is thought to be involved in tumour progression, such as S100A4, which is upregulated in many cancers including medulloblastoma and promotes angiogenesis and metastasis and S100P which is associated with metastasis in breast and pancreatic cancer." (PMID 17579622, 2007). "In the medulloblastoma cell line Daoy cells, Erb-B2 Receptor Tyrosine Kinase 2 (ERBB2) overexpression, an event associated with invasiveness and poor prognosis, increased the migration across basement membranes in vitro and the expression of prometastatic genes, such as S100A4." (PMID 33918416, 2021). "For example, DNA hypomethylation resulted in reduced S100A6 and S100A10 expression in medulloblastoma while somatic methylation controlled S100A2 and S100A4 expression in the normal cerebellum, showing tissue specific regulation." (PMID 34485305, 2021). "This study demonstrates a role for the epigenetic deregulation of three members of the S100 gene family, S100A4, S100A6 and S100A10, in medulloblastoma tumourigenesis." (PMID 17579622, 2007). "The expressions of S100A1, S100A4, S100A10, and S100A11 are regulated by DNA methylation in medulloblastoma and may have potential impacts on the disorder of telencephalon in cerebral hernia." (PMID 32867218, 2020). "Assessment of these genes in the non-neoplastic cerebellum (from which medulloblastomas develop) revealed strong somatic methylation affecting S100A2 and S100A4, whereas S100A6 and S100A10 were unmethylated." (PMID 17579622, 2007).
Obesity (7 papers, 2018 to 2024). Accumulation of substantial excess body fat. "For example, in patients suffering from obesity, increased serum levels of S100A4 were associated with liver damages and hepatic steatosis." (PMID 36232334, 2022). "The strengths include the large cohort of plasma samples from prepubertal children with obesity and the availability of additional physiologic parameters allowing to identify the associations between S100A4 and other surrogates of metabolic state." (PMID 32128247, 2020). "However, in one of these studies, the constitutive deletion of the S100A4 gene was reported to also aggravate obesity-associated hepatic inflammation in mice." (PMID 36232334, 2022). "Some S100 members (e.g., S100A4, S100A8/A9, S100A12 and S100B) have also been suggested to represent potential biomarkers of NAFLD-associated disorders such as obesity, type 2 diabetes, IR and inflammation." (PMID 36232334, 2022). "Certain S100 proteins, namely S100A4, S100A8/S100A9 heterodimer, and S100B, have been implicated in the pathophysiology of obesity-promoting macrophage-based inflammation via toll-like receptor 4 and/or receptor for advanced glycation end-products ligation." (PMID 35328627, 2022). "In inflammatory circumstances such as diabetes with obesity, plasma high mobility group box chromosomal protein 1 and S100A4, which are ligands of RAGE, are also increased, accompanied by AGEs." (PMID 34769147, 2021). "The S100 protein family members, S100A4, S100A8/A9 heterodimer, and S100B have all been implicated in the pathophysiology of obesity-associated inflammation via their interaction with RAGE." (PMID 34204735, 2021). "Circulating S100A4 levels were strongly correlated to HOMA‐IR in adult subjects with obesity and were maintained after adjusting for sex, age, and BMI (βstd = .42, P = .008)." (PMID 32128247, 2020). "Since WAT seems to play a role in the secretion and function of S100A4, the aim was to evaluate the effects of this adipokine in two different cell types with a relevant role in adipose tissue expandability during obesity: adipocytes and VSMC." (PMID 32128247, 2020). "Circulating S100A4 concentration was measured and significantly elevated levels in both prepubertal children (1.5‐fold, P = .002) and adult subjects with obesity (2.2‐fold, P < .001) were found compared with normal‐weight controls." (PMID 32128247, 2020). "Circulating S100A4 levels were increased in both children (P = .002) and adults (P < .001) with obesity compared with their normal‐weight controls." (PMID 32128247, 2020). "Indeed, constitutive deletion of S100A4 in mice aggravated hepatic steatosis, IR and obesity development induced by HFD feeding." (PMID 36232334, 2022). "Further studies will be necessary to determine whether S100A4 can be a therapeutic target for obesity." (PMID 32128247, 2020). "Our human data demonstrate that higher S100A4 levels are a marker of IR in adults with obesity but not in prepubertal children." (PMID 32128247, 2020). "While we have shown that knock-down of IRβ in S100a4-lineage cells is insufficient to recapitulate the phenotypes observed in obese/T2DM mice, future studies will be needed to determine if IRβ deletion, in the context of obesity, accelerates or slows tendinopathy development." (PMID 29907811, 2018).
osteoarthritis (7 papers, 2016 to 2025). A noninflammatory degenerative joint disease occurring chiefly in older persons, characterized by degeneration of the articular cartilage, hypertrophy of bone at the margins and changes in the synovial membrane. "S100A4 has been found to be upregulated in osteoarthritis chondrocytes (also in our study log2FC = 0.8, P = 1.9 × 10−15) and has been proposed to be a transcriptional regulator of MMP13, which is a key metalloprotease of extracellular matrix degradation." (PMID 35088088, 2022). "S100a4, a member of the S100 protein family, is involved in cartilage degradation of osteoarthritis pathophysiology." (PMID 33407721, 2021). "Analysis of bone tissue from osteoarthritis patients using microarrays and quantitative PCR indicated elevated expression of S100A4 as well as that of other wingless-type mouse mammary tumor virus integration site family-related proteins." (PMID 29204268, 2017). "Human articular chondrocytes upregulate S100A4 expression levels during rheumatoid- and osteoarthritis." (PMID 27331819, 2016). "When analyzing bone material from patients with osteoarthritis, by employing microarrays and quantitative PCR, the authors show an upregulation of S100A4, but also other Wnt-related genes." (PMID 27331819, 2016). "Moreover, elevated S100A4 expression in human articular chondrocytes during rheumatism and osteoarthritis leads to increased phosphorylation of protein tyrosine kinase-2 and MAPKs; it further activates NF-κB, increasing secreted MMP13 levels." (PMID 29204268, 2017). "Since osteoarthritis increases S100-A4 expression and MMP13 expression, we suggest that the lack of Y-27632-induced S100-A4 levels under hypoxic conditions may beneficially decrease the risk of MMP13 -mediated degradation of extracellular matrix." (PMID 28623370, 2017).
renal fibrosis (7 papers, 2020 to 2022). A final common manifestation of a wide variety of chronic kidney diseases characterized by glomerulosclerosis and tubulointerstitial fibrosis. "S100A4 was upregulated in the kidney in a murine model of renal fibrosis induced by folic acid nephropathy." (PMID 36078170, 2022). "In summary, we identified S100A4 as a novel profibrotic factor in the development of renal fibrosis." (PMID 36078170, 2022). "To further establish the role of S100A4 in kidney fibrosis in vivo, we investigated the effects of the S100A4 inhibitor niclosamide on S100A4 expression in mice with renal fibrosis." (PMID 36078170, 2022). "Furthermore, S100A4 is induced in the kidney in folic acid nephropathy while pharmacological inhibition of S100A4 suppresses activation of fibroblast and attenuates the progression of renal fibrosis." (PMID 36078170, 2022). "At present, we have uncovered an unrecognized role of S100A4 in renal fibrosis." (PMID 36078170, 2022). "Therefore, we examined the role of S100A4 in fibroblast activation and the development of renal fibrosis in vivo." (PMID 36078170, 2022). "However, the role of S100A4 in renal fibrosis is not known, and whether S100A4 could affect Smad3 signaling remains unclear." (PMID 36078170, 2022).
systemic sclerosis (7 papers, 2017 to 2024). A chronic disorder, possibly autoimmune, marked by excessive production of collagen which results in hardening and thickening of body tissues. "Recent studies highlight that the S100A4-dependent activation of RAGE and TLRs plays a critical role in fibrosis development in the lungs, liver, kidneys, and heart, and is also implicated in the progression of systemic sclerosis (SSc)." (PMID 39769332, 2024). "S100A4 is likewise up-regulated in the skin lesions of systemic sclerosis patients." (PMID 29204268, 2017). "Like in PF, S100A4, as a downstream mediator of the stimulatory effects of TGF-β1, amplifies TGF-β1-induced fibroblasts activation in systemic sclerosis." (PMID 36817136, 2023). "Targeting S100A4 by employing chemotherapeutic drugs such as MET, antibodies, or small-molecule inhibitors might provide a new potential therapy for systemic sclerosi, amyotrophic lateral sclerosis and cancers." (PMID 36817136, 2023).
amyotrophic lateral sclerosis (6 papers, 2019 to 2023). Amyotrophic lateral sclerosis (ALS) is a neurodegenerative disease characterized by progressive muscular paralysis reflecting degeneration of motor neurons in the primary motor cortex, corticospinal tracts, brainstem and spinal cord. "Silencing S100A4 with siRNA or blocking S100A4 with niclosamide inhibited fibroblasts activation in amyotrophic lateral sclerosis." (PMID 36817136, 2023). "The increased S100A4 expression in fibroblasts of amyotrophic lateral sclerosis patients suggests the contribution of S100A4-regulated pathways to neuroinflammation." (PMID 35546077, 2022). "Finally, we demonstrated the increased expression of S100A4 also in fibroblasts derived from amyotrophic lateral sclerosis (ALS) patients carrying SOD1 pathogenic variants." (PMID 31623154, 2019). "Furthermore, we investigated the expression and localization of S100A4 in a neurodegenerative disease characterized by a strong neuroinflammatory component, amyotrophic lateral sclerosis (ALS)." (PMID 31623154, 2019). "Furthermore, we found that S100A4 was significantly up-regulated in astrocytes and microglia in the spinal cord of a transgenic rat SOD1-G93A model of amyotrophic lateral sclerosis." (PMID 31623154, 2019).
chronic obstructive pulmonary disease (6 papers, 2015 to 2023). A chronic and progressive lung disorder characterized by the loss of elasticity of the bronchial tree and the air sacs, destruction of the air sacs wall, thickening of the bronchial wall, and mucous accumulation in the bronchial tree. "Various lung pathologies, such as plexogenic arteriopathy, chronic obstructive pulmonary disease, and several neoplastic conditions, have been associated with increased S100A4 levels and poor prognosis." (PMID 35053115, 2022). "S100A4 is a member of the S100 calcium-binding protein family and is increased in patients with chronic obstructive pulmonary disease (COPD)." (PMID 35165531, 2022). "S100A4-positive basal epithelial cells in the airway of chronic obstructive pulmonary disease patients were inversely correlated with FEV1/FVC." (PMID 35379204, 2022). "Therefore, the aim of the present study was to investigate S100A4 in the context of vascular remodeling within chronic obstructive pulmonary disease." (PMID 26483185, 2015).